TSC2 (TSC complex subunit 2)
Diseases named in the same sentence as TSC2 in open-access papers (continued):
Sharing a sentence is not in itself a finding about the gene and the disease.
renal angiomyolipoma (34 papers, 2007 to 2025). "Like kidney cysts, the hazard of having kidney angiomyolipomas was over twice higher in patients with TSC2 mutation than in those with TSC1 mutation (p = 0.029)." (PMID 38483608, 2024). "Renal angiomyolipomas affect approximately 60% of women with S-LAM, and renal angiomyolipoma cells from women with S-LAM also have TSC2 mutations, supporting the theory that LAM cells can metastasize to the lungs." (PMID 38877584, 2024). "Our small-molecule chemical screens reveal a sensitivity to inhibitors of checkpoint kinase 1/2 (CHK1/2), regulators of cell cycle, and DNA damage response, in both in vitro and in vivo models of TSC2-deficient renal angiomyolipoma (RA) tumors." (PMID 35359406, 2022). "Patients with TSC2 variants exhibit more severe renal phenotypes, especially those associated with renal angiomyolipomas (AML), and they often require nephrectomy/partial nephrectomy or mTOR medication." (PMID 35870981, 2022). "In the PNET dataset, 3.3% of cases harboured TSC1 or TSC2 mutations conferring sensitivity to the mammalian target of rapamycin (mTOR) inhibitor, everolimus, currently approved for renal angiomyolipomas and giant cell astrocytomas." (PMID 35849877, 2022). "First, a patient-derived cell line LAM-621 (LAM-associated renal angiomyolipoma) harboring a variant in TSC2 (p.Arg611Gln) rendering it unable to complex with TSC1, resulting in hyperactivated mTORC1 signaling." (PMID 34162842, 2021). "The mean age at diagnosis of renal angiomyolipomas was 13.3 years (median, 9 years, range <1–59 years) in patients with a TSC2 mutations, while it was 22.5 years (median 21 years, range <1–60 years) in those with a TSC1 mutations." (PMID 33041968, 2020). "Mutation studies have shown the occurrence and severity of TSC-associated renal angiomyolipomas and cysts to be higher among patients with TSC2 mutation than those with TSC1 mutation." (PMID 33041968, 2020). "Patients with TSC2 mutations in the transcription activation domain 1 coding genes, had increased renal angiomyolipoma [p = 0.019, OR = 3.519, 95%CI (1.226–10.101)]." (PMID 33679864, 2020). "Patients with TSC2 mutations were reported to exhibit a higher incidence and severity of both renal angiomyolipoma and cysts than those with TSC1 mutations." (PMID 33041968, 2020). "In a genetic association study, we demonstrated that a high expressing allele for IFN-γ is associated with a lower frequency of kidney angiomyolipomas in patients with known TSC2 mutations." (PMID 17986349, 2007). "Specifically, there is a fourfold increase in lung cysts (χ2 = 4.14 p = 0.04), a twofold increase in renal angiomyolipomas (χ2 = 14.14 p < 0.001), and a fivefold increase in liver angiomyolipomas (χ2 = 6.96 p = 0.008) if the patient has a TSC2 mutation compared to TSC1 mutation." (PMID 35292049, 2022). "Furthermore, more patients with TSC2 mutations received intervention for renal angiomyolipoma than those with TSC1 mutations." (PMID 33041968, 2020). "621-101 cells are TSC2-deficient cells derived from the renal angiomyolipoma of a patient with LAM." (PMID 27458154, 2016). "We also verified tuberous sclerosis complex 2-deficient renal angiomyolipoma (TSC2-null AML) cells as key VEGF-A secretors; VEGF-A was suppressed by sorafenib in both TSC2-null AML cells and LAMFs." (PMID 39903528, 2025). "TSC genes are also important: TSC1 and TSC2 mutations are implicated in tuberous sclerosis complex (TSC), presenting with simple cysts and renal angiomyolipomas, or in TSC2/PKD1 contiguous gene deletion syndrome, leading to early-onset cystic disease." (PMID 40268755, 2025). "High-throughput chemical screens in mTORC1-hyperactive patient renal angiomyolipoma-derived and Tsc2−/− MEFs cells identified compounds that selectively induce cell death through oxidative stress-dependent mechanisms within 72 h of drug treatment." (PMID 32807195, 2020).
renal angiomyolipoma (continued). "Similar to the overall sample, renal angiomyolipomas were asymptomatic in most patients with TSC1 (90.2%) and TSC2 (83.1%) mutations." (PMID 33041968, 2020). "Certain other clinical manifestations, including subependymal giant cell astrocytoma (SEGA), renal angiomyolipomas and cardiac rhabdomyomas, are more common in patients with TSC2 variants." (PMID 32313033, 2020). "We found that cardiac rhabdomyomas and renal angiomyolipomas were more common in patients with a PV in TSC2 than in TSC1 (7:1 and 4:1, respectively); in this, our results are similar to those of other published studies." (PMID 32313033, 2020). "Consistent with our in vitro data, we confirmed our observation of increased Nox4 protein expression and augmented ROS levels in the kidneys of Tsc2+/− mice and renal angiomyolipomas obtained from patients with TSC." (PMID 29491408, 2018). "We found that IGF2 has increased transcript expression in Tsc2-/- MEFs and TSC2— cells derived from renal angiomyolipoma of a LAM patient." (PMID 29758070, 2018). "Similar to kidney angiomyolipomas associated with TSC, the severity of kidney cystadenomas increases with age in A/J Tsc2+/- mice." (PMID 20146790, 2010). "Recent studies have found that heat shock protein-90 (HSP90) inhibitors have suppressive effects on TSC1/TSC2-deficient cell lines, while HSP90 dysregulation may be involved in the pathogenesis of TSC-associated renal angiomyolipoma." (PMID 37679848, 2023). "However, when compared to the differentially expressed genes in LAM lung cells and the upregulated genes in the known TSC2-null human LAM cell line – kidney angiomyolipoma (AML) cells, we found a number of genes in common." (PMID 33159078, 2020). "Similarly, we found elevated levels of Nox4 in the renal cortex of Tsc2+/− mice and in the renal angiomyolipomas from TSC patients." (PMID 29491408, 2018). "We conclude that sporadic renal angiomyolipoma usually have mutations in TSC2, but not TSC1 or RHEB, and have no other common genomic events, among those we searched for." (PMID 21949787, 2011). "Importantly, rapamycin treatment did not affect the expression of AdPLA2 and the production of PGE2 by TSC2-deficient mouse embryonic fibroblast (Tsc2−/−MEFs), rat uterine leiomyoma-derived ELT3 cells, and LAM patient-associated renal angiomyolipoma-derived “mesenchymal” cells." (PMID 25347447, 2014). "We show that renal angiomyolipomas from TSC patients and kidney cortex from Tsc2+/− mice exhibit elevated levels of reactive oxygen species (ROS)." (PMID 29491408, 2018). "In the present study, we show increased levels of ROS in the renal angiomyolipomas of patients with TSC and the kidney cortex of Tsc2 heterozygous mice." (PMID 29491408, 2018). "Our results indicate that genetic alterations in TSC2/TSC1 are the primary and essential driver genetic events for development and progression of renal angiomyolipoma." (PMID 27494029, 2016). "Sporadic, non-TSC associated, renal angiomyolipoma and LAM are due nearly exclusively to mutations in TSC2." (PMID 27494029, 2016). "Analysis of the 16 renal angiomyolipomas from one patient (P13), who has TSC, revealed a non-mosaic germline TSC2 deletion mutation (c.5135delC) that was also seen in normal tissue." (PMID 27494029, 2016). "Both the renal cystadenomas that occur in Tsc2+/- mice and kidney angiomyolipomas that occur in individuals with TSC tend not to be present at young ages but develop over time." (PMID 17986349, 2007).
Renal cyst (32 papers, 2013 to 2025). A fluid filled sac in the kidney. "Thefrequency of angiomyolipomas and renal cysts tends to be higher when the TSC2 gene is involved, compared to TSC1 mutations." (PMID 40822828, 2025). "The mouse model of TSC-associated renal cysts were constructed by knocking out Tsc2 specifically in renal tubules (Tsc2f/f; ksp-Cre)." (PMID 39333852, 2024). "In this study, we discovered the mTOR/miR-142-3p/PRAS40 signaling cascade and evaluated its significance in TSC2 deficiency-induced renal cyst formation." (PMID 39333852, 2024). "Examination of murine models of renal cystic disease associated with either Tsc1 or Tsc2 directly or indirectly has revealed that cyst development is linked to particular nephron segments, with all tubular segments implicated in Tsc cyst formation." (PMID 39201746, 2024). "Our data suggest that female sex, age, and TSC2 mutations are associated with a higher risk for most findings except pulmonary nodules and renal cysts." (PMID 35292049, 2022). "We previously reported that loss of the Tsc2 gene resulted in renal cystic disease via a novel EV-mediated pathway, and the mutant cells produced more EVs with an altered proteome." (PMID 34262466, 2021). "In contrast, loss of Tsc1 or Tsc2 enhances cilia length in mouse embryonic fibroblasts (MEFs), and intriguingly, clinically there is a relatively low frequency of renal cyst and RCC formation in TSC patients." (PMID 23369289, 2013). "Multiple renal cysts are infrequently observed in the general populace but may be present in TSC patients harboring mutations in TSC1 or TSC2 or as part of contiguous gene deletion syndromes affecting the TSC2 and PKD1 genes." (PMID 39201746, 2024). "However, the study’s findings cannot be extrapolated to TSC cystic kidney disease caused by Tsc2 deletion." (PMID 37290438, 2023). "Additionally, individuals with a severe and early diagnosed form of the renal cystic disease were also found to display TSC2 gene mutation." (PMID 36422197, 2022). "Hartman found that Rapamycin enhanced cilia formation in TSC1 and TSC2 null cells and concluded that the efficacy of mTOR inhibitors on renal cystic disease in patients carrying a TSC mutation or PKD1/TSC2-CGS may differ from its efficacy in ADPKD." (PMID 26077033, 2015). "Given that PRAS40 depletion decreased PCNA expression in Tsc2-depleted renal cysts, we checked the significance of PRAS40 in the proliferation of Tsc2−/− MEFs." (PMID 39333852, 2024). "Both total body tamoxifen-inducible Cagg-Cre and kidney epithelium-specific KSP-Cre models of Tsc2 inactivation exhibit significant cystic kidney disease burden, decreased body weight and decreased survival." (PMID 38195686, 2024). "Analysis of TSC2 patients with severe renal cystic disease showed they can have deletions also disrupting PKD1; a contiguous gene syndrome (CGS)." (PMID 26077033, 2015). "A number of tumor suppressor genes that have established roles in renal tumorigenesis, namely VHL, TSC1, TSC2 and FLCN, also predispose to renal cyst formation, a common hallmark of ciliopathy syndromes." (PMID 23369289, 2013). "In addition, PRAS40 contributed to the proliferation of Tsc2−/− MEFs and the renal cyst epithelial cells, and cystogenesis of Tsc2-deleted mouse kidneys." (PMID 39333852, 2024). "To build on these initial studies of Tsc‐associated renal cystic disease in the mouse model system, we employed two newly developed mouse Tsc‐renal cystic disease models, one that disrupts the Tsc2 gene in renal principal cells, and the other that disrupts the Tsc1 gene in renal pericytes." (PMID 30675765, 2019). "Similarly, loss of tumor suppressor genes such as TSC1 and TSC2 is not always accompanied by the development of renal cysts and overgrowth." (PMID 28353628, 2017). "These mice developed renal cysts that were primarily composed of A-IC cells that express both TSC1 and TSC2." (PMID 40243914, 2025).
Renal cyst (continued). "In fact, examination of renal cysts in mouse models of TSC indicates that they are composed of cells that express both TSC1 and TSC2." (PMID 40243914, 2025). "Contiguous deletion of TSC2/PKD1 was found in one individual, who presented with renal cysts at age 6 months, hypertension at 14 months, and developed a clinical course akin to autosomal dominant polycystic kidney disease." (PMID 37386496, 2023). "In a TSC renal cyst mouse model and TSC neural mouse model, wild‐type cells of the microenvironment were observed to take on an EV‐mediated Tsc2‐mutant disease phenotype." (PMID 37337371, 2023). "The studies that are discussed in this review article demonstrate that in TSC renal cysts, A-IC cells that express both TSC1 and TSC2 constitute the cyst epithelium, and that FOXI1 plays a critical role in the process of cystogenesis." (PMID 38028758, 2023). "Kidney cysts are usually composed of cells that express intact TSC1 and TSC2 proteins in both mouse models, as well as in humans with TSC renal cystic disease." (PMID 38028758, 2023). "Two male patients aged 7.7 and 9.3 years had genetically confirmed contagious genes syndrome (deletion involving TSC2 and PKD1 genes) with very large renal cysts (maximal cyst diameter −35 and 44 mm, respectively)." (PMID 34912759, 2021). "Cystic kidney disease is the second most frequent renal manifestation of TSC and can be triggered by the biallelic inactivation of TSC1/TSC2 alone or as the result of deletion events that also affect the PKD1 locus located adjacently in chromosome 1646." (PMID 34764250, 2021). "This becomes more apparent considering that the renal cyst epithelia in mice with cell-specific knockout of Tsc1 or Tsc2 genes in principal cells (PCs) or pericytes are almost entirely composed of A-ICs that express both TSC1 and TSC2." (PMID 40243914, 2025). "In contrast, this same difference is not observed in the case of renal cysts, where prevalence amongst TSC1 and TSC2 patients is almost equal at 27% and 29%, respectively, an insignificant difference at p < 0.05 (Z = −0.18, df = 1, p = 0.86)." (PMID 35440050, 2022).
polycystic kidney disease (26 papers, 2009 to 2025). A usually autosomal dominant and less frequently autosomal recessive genetic disorder characterized by the presence of numerous cysts in the kidneys leading to end-stage renal failure. "A study found that large mutational deletion of the TSC2 gene is correlated with the development of early-onset polycystic kidney disease in which the adjacent PKD1 gene was also affected by this deletion." (PMID 36422197, 2022). "Conversely, point mutations of TSC2 were detected in four out of eight patients with classic polycystic kidney disease." (PMID 36232477, 2022). "As expected polycystic kidney disease was only found in those with TSC2 mutations because it is the result of a deletion stretching across the TSC2 and PKD1 genes on chromosme 16 (The “contiguous gene syndrome”)." (PMID 33041968, 2020). "Compared with patients with a TSC1 mutation, those with TSC2 mutations had a higher occurrence of multiple renal cysts (33.6 vs. 13.3%) and polycystic kidney disease (4.7 vs. 0%)." (PMID 33041968, 2020). "Moreover, there were 3 patients with TSC2 variants who had polycystic kidney disease (PKD)." (PMID 35870981, 2022). "Regarding renal manifestations, extensive deletions affecting both the TSC2 gene and the adjacent PKD1 gene are closely linked to the occurrence of polycystic kidney disease." (PMID 40364023, 2025). "The TSC2 gene is in close proximity to the PKD2 gene on chromosome 16, which causes the autosomal dominant form of polycystic kidney disease, potentially leading to a contiguous gene deletion syndrome." (PMID 40141713, 2025). "The majority of the patients with a pathologic result in genetic testing were positive for a pathogenic variant in the TSC2 gene, including five cases of contiguous gene deletion syndrome of TSC2 and PKD1 causing both polycystic kidney disease and TSC." (PMID 39726678, 2024). "NEK1 and CTNNB1, together with AXIN1, GSK3B and TSC2, participate in the Wnt signaling pathway in urological cancer cells and polycystic kidney disease (PKD)." (PMID 26317783, 2015). "Three of these mutations (37.5 %) were deletions disrupting not only TSC2 gene but also adjacent PKD1 gene, causing polycystic kidney disease in these patients." (PMID 25227171, 2014). "In 2–3% of patients with TSC, TSC2/PKD1 contiguous gene syndrome (CGS) is found as a distinct disease entity with clinical features typical of TSC combined with severe and early polycystic kidney disease, almost always associated with early progression to end-stage renal disease." (PMID 41227201, 2025). "In addition, the proximity of the TSC2 gene to the PKD1 gene, mutations of which cause polycystic kidney disease (PKD), results in a contiguous gene syndrome (CGS)." (PMID 41227201, 2025). "In addition, a contiguous gene deletion syndrome (deletion of both TSC2 and PKD1 genes, causing both TSC and polycystic kidney disease) was identified in 5 cases." (PMID 39726678, 2024). "Some TSC2 missense mutations (i.e., p.Arg905Gln and p.Gln1503Pro); however, not all missense mutations are associated with milder disease phenotypes, and TSC2/PKD1 contiguous gene deletion is associated with polycystic kidney disease." (PMID 36232477, 2022). "Some patients with TS carry a contiguous germline deletion that affects both the TSC2 gene and the adjacent gene, polycystic kidney disease type 1 (PKD1), resulting in a polycystic kidney phenotype that leads to early renal insufficiency." (PMID 20062701, 2009). "Contiguous gene deletion syndrome, characterized by both TSC and polycystic kidney disease, affects up to 5% of TSC patients and has been diagnosed in the two patients with TSC2 segmental deletions encompassing PKD1 exon 46, assisted in a multispecialty clinic." (PMID 39596632, 2024). "The PKD1 gene is proximal tothe TSC2 gene on chromosome 16, and may lead to the possibility ofTSC/PKD contiguous gene syndrome and the development of polycystic kidney disease(PKD)." (PMID 35638823, 2022).